PURA (purine rich element binding protein A)
Diseases named in the same sentence as PURA in open-access papers (continued):
Sharing a sentence is not in itself a finding about the gene and the disease.
acute myeloid leukemia (3 papers, 2020 to 2025). Acute myeloid leukemia (AML) is a group of neoplasms arising from precursor cells committed to the myeloid cell-line differentiation. "In addition, deletions or mutations in PURA have now been implicated in acute myeloid leukemia (AML), myelodysplastic syndrome (MDS) and PURA syndrome characterized by neonatal hypotonia, respiratory compromise, feeding difficulties, severe intellectual disability and epilepsy." (PMID 33142842, 2020). "PURα was initially recognized as a tumor suppressor in acute myeloid leukemia (AML) and prostate cancer (PC)." (PMID 39844051, 2025). "Abnormal PURα expression is also involved in the progression of several cancers, such as acute myeloid leukemia (AML) and prostate cancer, and our previous results have shown that overexpression of PURα promotes ESCC progression." (PMID 35945453, 2022).
prostate carcinoma (3 papers, 2022 to 2025). A carcinoma that arises from epithelial cells of the prostate gland. "By exploring the Oncomine database, PURα mRNA levels were significantly lower in HRPC samples than in Hormone-naive Prostate Cancer (HNPC) samples in a large cohort." (PMID 39844051, 2025). "We firstly found that purine-rich element binding protein alpha (PURα), encoded by PURA, was detected in the NM composition within both androgen-dependent and -independent prostate cancer cell lines." (PMID 39000020, 2024). "In summary, PURα is a nuclear matrix protein identified in prostate cancer cells." (PMID 39000020, 2024). "Additionally, according to the expression analysis, a decrease in the nuclear expression of PURα in mCRPC specimens may indicate its tumor suppressive role in the progression to CRPC in prostate cancer." (PMID 39000020, 2024). "Since PURα seems to have oncogenic roles in ESCC cells, which is the opposite to the role seen in prostate cancer, the role of PURα, especially as a component of the NM, remains to be elucidated and further investigation needs to be performed." (PMID 39000020, 2024). "Actually, when compared with hormone-naïve and CRPC prostate cancer specimens, CRPC specimens with higher AR expression levels had reduced PURα m-RNA, cytosolic rather than nuclear localization of the PURα protein, and occupancy by PURα of the suppressor element in the 5′-UTR of the human AR gene." (PMID 39000020, 2024).
abscess (2 papers, 2019 to 2025). An inflammatory process characterized by the accumulation of pus within a newly formed tissue cavity which is the result of a bacterial, fungal, or parasitic infection or the presence of a foreign body. "The purine biosynthesis mutant strains in purA and purH exhibited significant attenuation of virulence in a murine abscess model." (PMID 40698813, 2025). "S. aureus purB mutants have been recently shown by our group to have reduced pathogenesis, and purA mutants were found to be attenuated in a S. aureus murine abscess study." (PMID 30766531, 2019).
Alzheimer disease (2 papers, 2021 to 2022). A progressive, neurodegenerative disease characterized by loss of function and death of nerve cells in several areas of the brain leading to loss of cognitive function such as memory and language. "Additionally, circCwc27 directly binds to purine-rich element-binding protein A (Pur-α), influencing its distribution by trapping Pur-α in the cytoplasm and then regulating Alzheimer’s disease genes transcription." (PMID 36139074, 2022). "In the end, totaly 656 differentially expressed genes between HT22 and Purα-KO HT22 cells have been found, which include 7 Alzheimer’s disease (AD)-related genes and 5 Aβ clearance related genes." (PMID 34108502, 2021).
autoimmune disease (2 papers, 2023). A disorder resulting from loss of function or tissue destruction of an organ or multiple organs, arising from humoral or cellular immune responses of the individual to their own tissue constituents. "Investigating the TFs regulating the fine‐mapped autoimmune disease enhancers, we find the known immune response TFs NFKB1/2, RELB and IRF8, but also MBD2, ZBT14 and PURA, which we identified as important TFs for predicting response to infection." (PMID 37073532, 2023).
cognitive deficit (2 papers, 2022 to 2026). "Dominant PURA variants (encoding purine-rich element-binding protein A) cause a neurodevelopmental disorder with hypotonia, cognitive impairment, and variable neuromuscular symptoms." (PMID 41575592, 2026).
glioblastoma (2 papers, 2015 to 2025). The most malignant astrocytic tumor (WHO grade IV). "Purα is a regulator of cell proliferation; its ectopic expression causes cell cycle arrest at either the G1/S or G2/M transition points and suppresses the growth of several transformed and tumor cells including glioblastomas." (PMID 26337085, 2015).
myelodysplastic syndrome (2 papers, 2020 to 2025). A clonal hematopoietic disorder characterized by dysplasia and ineffective hematopoiesis in one or more of the hematopoietic cell lines. "In 2001, deletion of the PURA loci was observed in a majority of patients with myeloid disorders, suggesting its involvement in the progression of myelodysplastic syndromes (MDS) and acute myelogenous leukemia (AML)." (PMID 39844051, 2025).
status epilepticus (2 papers, 2013 to 2020). Status epilepticus is defined as a continuous seizure lasting more than 30 min, or two or more seizures without full recovery of consciousness between any of them. "The decrease of PURA reduces postsynaptic density protein 95, which contributes to neuronal cell loss after status epilepticus and KA administration." (PMID 23970931, 2013).
viral infection (2 papers, 2010 to 2022). "Viral infection alters not only the use of PURA promoters but also the generation of different non-coding RNAs from 5'-UTRs of the resulting transcripts." (PMID 21062477, 2010). "Analysis of the total RNA recovered from MCMV infected 3T3 cells demonstrates that PURA transcription is altered in response to viral infection." (PMID 21062477, 2010). "The role of one of the human homologs, PurA, in promoting stress granule formation that is detrimental to viral infection may provide hints on how AePur regulates infection intensity." (PMID 36121894, 2022). "We therefore determined whether or not interferon regulatory factor (IRF) proteins, frequently produced or activated as a result of viral infection, might directly or indirectly alter use of PURA promoters." (PMID 21062477, 2010). "We hypothesize that Purα expression is controlled differently depending on various states of cell environment, including growth-altering signals or viral infection and that such control is mediated effectively by independent modes of transcriptional promotion." (PMID 21062477, 2010). "Considering that Purα is required in many processes involving ss-RNA or DNA, the presence of these binding sites suggests that the cell may actually optimize survival during viral infection by regulating the availability of Purα." (PMID 21062477, 2010). "PURA TSS II is near several DNA elements that potentially, bind proteins generated and/or activated by an innate immune response to viral infection." (PMID 21062477, 2010). "The decrease in expression of pGL3-PURA in the presence of overexpressed IRF-3, IRF-5, and IRF-7 and the specific binding of IRF-3 to sequence near TSS II led us to investigate whether or not viral infection could affect PURA transcription." (PMID 21062477, 2010).
atherosclerosis (1 paper, 2023). A disease characterized by the build-up of fatty material and calcium deposition in the arterial wall resulting in partial or complete occlusion of the arterial lumen. "In addition, genes predicted to be targeted by the miR-17-5p, not previously associated with atherosclerosis, include ARID4B, E2F, GATA1, MEF2D, NR1I2, PURA, and RBL2." (PMID 36859458, 2023).
autism spectrum disorder (1 paper, 2025). A spectrum of developmental disorders that includes autism, and Asperger syndrome.
autosomal dominant mental retardation (1 paper, 2022). "Variants in the PURA gene have been linked to autosomal dominant mental retardation 31, which has an autosomal dominant inheritance pattern and correlates with the patient’s phenotype." (PMID 35884678, 2022).
bladder carcinoma (1 paper, 2019). "Gaballah identified candidate genes: PURA, SRPK2, TRAK1, BRD2, and UPF3 in progression and invasiveness of bladder carcinoma based on DEGs acquired by comparing invasive and noninvasive samples by Limma R packages in 2016." (PMID 30723390, 2019).
demyelinating disease (1 paper, 2021). A broad group of disorders that affect the myelin sheaths that cover the neurons. "Moreover, PURA has been demonstrated to regulate MBP gene transcription and, under particular immunosuppressive conditions, into the demyelinating disease named progressive multifocal leukoencephalopathy, which precisely consists in the degeneration of the oligodendroglial cells." (PMID 34063504, 2021).
gastric cancer (1 paper, 2025). A primary or metastatic malignant neoplasm involving the stomach. "Kitajima has uncovered that the interaction between TM4SF1-AS1 and PURα promoted the formation of SGs, inactivated stress-responsive mitogen-activated protein kinases (MAPK) signaling, and inhibited cellular apoptosis in gastric cancer (GC) cells." (PMID 39844051, 2025).
HCMV infection (1 paper, 2010). "Here we identify three functionally distinct PURA promoters and show that these are utilized differentially in human cell types and that they respond differently to cytomegalovirus infection." (PMID 21062477, 2010).
heart failure (1 paper, 2023). Inability of the heart to pump blood at an adequate rate to meet tissue metabolic requirements. "MHC alpha is downregulated in a PURA-dependent manner in heart failure as well." (PMID 36768582, 2023). "While PURA is ubiquitously expressed, PURB is expressed in the fibroblasts, myoblasts, and in myocardiocytes during heart failure, and PURG is expressed at low levels across the tissues." (PMID 36768582, 2023).
hypomyelinating leukodystrophy 10 (1 paper, 2024). Any leukodystrophy in which the cause of the disease is a mutation in the PYCR2 gene. "Purine-Rich Element-Binding Protein A (PURA) causes a neurodevelopmental disorder with neonatal respiratory insufficiency, hypotonia, and feeding difficulties (MIM#616158), and Pyrroline-5-Carboxylate Reductase 2 (PYCR2) causes hypomyelinating leukodystrophy 10 (MIM#616420)." (PMID 37563452, 2024).
infantile epileptic encephalopathy (1 paper, 2021). an epileptic condition characterized by epileptiform abnormalities associated with progressive cerebral dysfunction. "Finally, next-generation sequencing (NGS) of patients with severe psychomotor development and infantile epileptic encephalopathy revealed a large number of de novo mutations in PURA, confirming the association of PURA with 5q31 microdeletion syndrome." (PMID 34571966, 2021).
kidney infection (1 paper, 2022). "For instance, the inactivation of purA causes the lower expression of a broad spectrum of genes (e.g., energy production and conversion) and attenuates the ability of S. aureus to cause kidney infection in mice." (PMID 36140695, 2022).
lung adenocarcinoma (1 paper, 2010). A carcinoma that arises from the lung and is characterized by the presence of malignant glandular epithelial cells. "We sought to determine whether TSS II, located 1,249 bp upstream of the Purα translational start codon, is utilized similarly in normal human lung tissue and lung adenocarcinoma." (PMID 21062477, 2010).
meningitis (1 paper, 2016). A disorder characterized by acute inflammation of the meninges of the brain and/or spinal cord. "Both purA (adenylosuccinate synthetase) and pyrG (CTP synthase) were associated with attenuated S. pneumonia replication during experimental meningitis and pyridoxine is important for the functioning of nerves." (PMID 27688977, 2016).
Myelodysplasia (1 paper, 2022). Clonal hematopoietic stem cell disorders characterized by dysplasia (ineffective production) in one or more hematopoietic cell lineages, leading to anemia and cytopenia. "Genes of unknown significance that were consistently selected by the models include PURA (in UC), which plays a role in the cell cycle and may cause myelodysplasia in case of hemizygosity." (PMID 36140740, 2022).
PURA-related neurodevelopmental disorders (1 paper, 2023). "PURA-related neurodevelopmental disorders (PURA-NDDs) are a rare genetic disease caused by pathogenic autosomal dominant variants in the PURA gene or a deletion encompassing the PURA gene." (PMID 36768582, 2023).
Salmonella Infections (1 paper, 2023). Infections with bacteria of the genus SALMONELLA. "Furthermore, the expression of genes in the PURA regulon were upregulated upon Salmonella infection to a similar extent as the genes in the NFKB2 regulon, which is a known pro‐inflammatory TF." (PMID 37073532, 2023).
salmonellosis (1 paper, 2012). Infections with bacteria of the genus salmonella. "In contrast, the double mutant Salmonella purA ssaGH was initially largely cleared from spleen and liver consistent with early killing during acute salmonellosis, but maintained largely constant bacterial tissue loads thereafter suggesting limited net growth." (PMID 22911873, 2012).
Sepsis (1 paper, 2010). Sepsis is defined as life-threatening organ dysfunction caused by a dysregulated host response to infection. "As expected, the control strain with the transposon Tn5EZ insertion in purA was unable to grow in the absence of exogenous purines and was also avirulent in the mouse sepsis model of infection (data not shown)." (PMID 20552019, 2010).
sialorrhea (1 paper, 2024). "In addition to the classical PURA deficiency phenotype, our patient exhibited pronounced sialorrhea and seizures, which were effectively treated with the ketogenic diet (KD)." (PMID 39062627, 2024).
infection (15 papers, 2010 to 2025). The state of being infected such as from the introduction of a foreign agent such as serum, vaccine, antigenic substance or organism. "These include mutations in purA, purB, and clpX, which have been shown to be important in various models of infection (12, –, 14)." (PMID 34101490, 2021). "When LAP was inhibited by knockdown of Rubicon, both the PhoP-deficient and the PurA-deficient strains induced more severe infections in the zebrafish host." (PMID 31428591, 2019). "Purine synthesis seemingly plays an important role for intracellular growth of L. monocytogenes and a L. monocytogenes serotype 4b strain with a mutation of purA is known to be strongly attenuated in the infection of mice." (PMID 24498259, 2014). "While both attenuated strains triggered recruitment of GFP-Lc3 in a Rubicon-dependent manner, they had opposite effects on the level of GFP-Lc3 recruitment, which was increased in the infection with PhoP-deficient bacteria and reduced in response to PurA-deficient bacteria." (PMID 31428591, 2019). "In the SS2 virulent strain S735, treR and purA were identified as VFs by a novel signature-tagged mutagenesis system, and S735 with mutations in these genes had attenuated virulence in both mouse and piglet infection models." (PMID 30280091, 2018). "To test this hypothesis we transduced 12 mutations into the parental Salmonella purA ssaGH strain, and determined persistence capabilities of the resulting strains in competitive infections with mixtures with the parental strain." (PMID 22911873, 2012). "In intravenously infected mice, purA mutants were highly attenuated, similar to actA mutants, but displayed distinct growth kinetics during the course of infection." (PMID 40910949, 2025). "Among the TFs that are less well known for their role in macrophages, we find PURA for many of the infection settings." (PMID 37073532, 2023). "In the same line, the downregulation of adenylosuccinate synthetase (purA), having a crucial role in the purine biosynthesis, reduces bacterial growth and attenuates pathogenicity at all stages of infection such as colonization, invasion, and internalization." (PMID 29587743, 2018). "Three genes (purA, purB, and pabA) were subsequently found to be required for pathogenesis in the zebrafish embryo infection model." (PMID 28808156, 2017). "The asRNA anti0055 is located antisense of lmo0055 or purA, an adenylosuccinate synthetase, important in the de novo synthesis of purine nucleobases, which also plays roles in infection and intracellular growth." (PMID 24498259, 2014). "At each time point during the infection, the intracellular bacterial loads of the S12023 aroA and S12023 purA bacteria were heavily skewed towards low intracellular densities." (PMID 23236281, 2012). "It is notable that levels of Purα protein increase modestly from 3 hrs through 9 hrs post infection, although levels of its mRNA are decreasing until at least 5 hrs." (PMID 21062477, 2010). "Western blot analysis of proteins isolated from MCMV infected 3T3 cells at 1 hr, 3 hr, 5 hr, and 9 hr pi, and from mock infected cells shows that Purα levels drop dramatically shortly after infection." (PMID 21062477, 2010). "In known instances where Purα function is co-opted by viruses, e.g., upon infection with HIV-1 or JC virus, viral proteins bind to and alter the function of Purα." (PMID 21062477, 2010). "Salmonella purA ssaGH ribB defective for 3,4-dihydroxy-2-butanone 4-phosphate synthase which is involved in riboflavin biosynthesis, was cleared within one day post infection to very low levels in both spleen and liver, but stabilized thereafter particularly in liver." (PMID 22911873, 2012). "However, Salmonella purA ssaGH asd was only partially cleared during the first day post infection which might reflect residual proliferation of some Salmonella and/or difficulties in establishing a suitable systemic niche." (PMID 22911873, 2012).
infection (continued). "al showed that purA and purB are essential for growth of JE2 in human and rabbit blood, and pathogenesis in a zebrafish embryo infection model." (PMID 30625152, 2019). "Following infection by MCMV, the level of PURA transcript from TSS II declines rapidly with a corresponding decrease in level of Purα protein." (PMID 21062477, 2010). "Infection of NIH 3T3 cells with mouse cytomegalovirus results in a rapid decrease in levels of mPURA mRNA and Purα protein." (PMID 21062477, 2010). "Biochemical complementation of the purA and purB mutants was not successful in the zebrafish infection model, likely due to poor diffusion of nucleobases into zebrafish embryos (data not shown)." (PMID 28808156, 2017).